FAR2P2 (fatty acyl-CoA reductase 2 pseudogene 2)
Gene: Transcribed unprocessed pseudogene on chromosome 2 (130,419,071 to 130,431,363, reverse strand). Ensembl gene ENSG00000178162.
Diseases named in the same sentence as FAR2P2 in open-access papers:
FAR2P2 is named in the same sentence as 1 disease in open-access papers, as found by Europe PMC text mining. Sharing a sentence is not in itself a finding about the gene and the disease. The quoted sentences say what the papers report.
cervical cancer (1 paper, 2023). A primary or metastatic malignant neoplasm involving the cervix. "The results revealed that PCK1, MT1A, AL096855.1, AC096711.2, FAR2P2, and AC099568.2 not only play a key role in the PPAR signaling pathway but also show good predictive value in cervical cancer patients." (PMID 37292383, 2023).